PSMC4 (proteasome 26S subunit, ATPase 4)
Diseases named in the same sentence as PSMC4 in open-access papers:
PSMC4 is named in the same sentence as 47 diseases in open-access papers, as found by Europe PMC text mining. Sharing a sentence is not in itself a finding about the gene and the disease. The quoted sentences say what the papers report.
breast carcinoma (7 papers, 2007 to 2025). "Recent studies have implicated PSMC4 in various cancers, including breast cancer, endometrial cancer, prostate carcinoma, and oral squamous cell carcinoma, where its dysregulation contributes to tumorigenesis and cancer progression." (PMID 40386560, 2025). "Research has revealed that elevated expression of PSMC4 correlates positively with reduced survival rates in breast cancer patients." (PMID 40386560, 2025). "Both mRNA and protein levels of PSMC2, PSMC3, PSMC4, PSMC5, and PSMC6 were significant in cancer tissues, and PSMC1, PSMC3, PSMC4, PSMC5, and PSMC6 overexpression was associated with poor prognoses of breast cancer patients." (PMID 34329194, 2021). "PSMC4 (proteasome 26S subunit, ATPase, 4), was recognized as a house keeper gene in breast cancer, but was detected upregulated in prostate carcinoma, which might promote tumorigenesis." (PMID 32549787, 2020). "Previous findings on PSMC4 include that high levels of PSMC4 (and other PSMC) transcripts were positively correlated with poor breast cancer survival." (PMID 37129360, 2023). "According to our results from an Oncomine analysis of mRNA expressions of PSMC2, PSMC3, PSMC4, PSMC5, and PSMC6, these members are highly upregulated in breast cancer tissues; therefore, we chose breast cancer to perform further bioinformatics analyses." (PMID 34329194, 2021). "Meanwhile, we discovered that high levels of PSMC1, PSMC3, PSMC4, PSMC5, and PSMC6 transcripts were positively correlated with poor survival, which likely shows their importance in breast cancer development." (PMID 34329194, 2021). "The present findings showed significantly higher expression profiles of PSMC2, PSMC3, PSMC4, PSMC5, and PSMC6 in breast cancer compared to normal breast tissues." (PMID 34329194, 2021). "Indeed, PSMC2, PSMC3, PSMC4, PSMC5, and PSMC6 were recently reported as highly expressed in breast cancer, which correlated with worse outcomes." (PMID 36498916, 2022). "The Kaplan–Meier plotter database also showed that PSMC1, PSMC3, PSMC4, PSMC5, and PSMC6 had high expression levels in breast cancer tissues may have oncogenic roles in breast cancer progression." (PMID 34329194, 2021).
endometrial cancer (5 papers, 2020 to 2021). Primary or metastatic malignant neoplasm involving the endometrium (mucous membrane that lines the endometrial cavity). "In previous bioinformatics studies, PSMC4 has been identified as part of the immune gene signature for predicting prognosis in endometrial cancer." (PMID 34496868, 2021). "Immunohistochemical analysis based on The Human Protein Atlas database enumerated a significant upregulation of PSMC4, NR3C1, SBDS, and CBLC in endometrial cancer tissues, relative to normal tissues." (PMID 33292199, 2020). "PSMC4, PUM1 and IPO8 were identified as the best reference genes combination for type 1 endometrial cancer (grades 1, 2 and 3), whereas for type 2 endometrial cancer (serous and carcinosarcoma), UBC, MRPL19, PGK1 and PPIA were the best reference genes combination." (PMID 32439920, 2020).
prostate carcinoma (4 papers, 2020 to 2025). A carcinoma that arises from epithelial cells of the prostate gland. "Previous research across breast and prostate cancers suggests that elevated PSMC4 levels are closely linked with tumor progression." (PMID 40386560, 2025). "This is consistent with previous research showing that PSMC4 knockout inhibits proliferation, cell cycle progression, and in vivo migration of prostate cancer cells while inducing apoptosis." (PMID 40386560, 2025). "However, the function of PSMC4 in prostate carcinoma (PCa) progression requires further clarification." (PMID 37436074, 2023). "Additionally, evidence suggests that PSMC4 may influence the progression of prostate cancer by modulating the CBX3-EGFR-PI3K-AKT-mTOR signaling pathway." (PMID 40386560, 2025).
Parkinson disease (3 papers, 2019 to 2023). A progressive degenerative disorder of the central nervous system characterized by loss of dopamine producing neurons in the substantia nigra and the presence of Lewy bodies in the substantia nigra and locus coeruleus. "HNRNPA1 is involved in protein translation, whereas ATG4B regulates AMPK signaling and energy homeostasis, and PSMC4 physically interacts with AMPK and is involved in Parkinson’s disease." (PMID 31097295, 2019).
diabetes (2 papers, 2020 to 2025). "In the group enriched with diabetic patients (6 out of 9 patients), seven proteasome genes (PSME4, PSMA7, PSMB4, PSMB6, PSMC4, PSMD7 and PSMD8) and three genes previously associated with common diabetes (SNX17, PARK7/DJ-1 and ATP5B) were highly expressed." (PMID 32302349, 2020).
lung adenocarcinoma (2 papers, 2020 to 2025). A carcinoma that arises from the lung and is characterized by the presence of malignant glandular epithelial cells. "In conclusion, this study offers valuable insights into the expression of the PSMC4 gene in lung adenocarcinoma and its association with clinical pathological features, immune cell infiltration, and functional enrichment." (PMID 40386560, 2025). "These insights are critical for advancing our understanding of the molecular dynamics associated with PSMC4 in the progression of lung adenocarcinoma." (PMID 40386560, 2025). "In this study, we investigated the expression levels of PSMC4 in lung adenocarcinoma and assessed its associations with clinicopathological features, immune cell infiltration, and functional enrichment." (PMID 40386560, 2025). "The findings suggest that PSMC4 may serve as a promising diagnostic biomarker and therapeutic target for lung adenocarcinoma." (PMID 40386560, 2025). "The results of this study lay the groundwork for further exploration of PSMC4’s role in cancer biology and its potential to enhance the diagnosis and treatment of lung adenocarcinoma." (PMID 40386560, 2025). "This correlation underscores the potential of PSMC4 as a prognostic marker for tumor progression in lung adenocarcinoma." (PMID 40386560, 2025). "Our investigation elucidates the relationship between the expression of PSMC4 and various clinical-pathological characteristics in lung adenocarcinoma." (PMID 40386560, 2025). "Utilizing ssGSEA, our study assessed the presence of 24 immune cell types within lung adenocarcinoma tissues, concurrently exploring the relationship between PSMC4 expression and immune cell infiltration using Spearman correlation analysis." (PMID 40386560, 2025). "In subgroup analyses, high PSMC4 expression particularly compromised prognoses in patients with early-stage lung adenocarcinoma (N0/N1 and pathological stages I-II), indicating its potential as an early adverse prognostic marker." (PMID 40386560, 2025). "First, the research predominantly relies on bioinformatics analyses and lacks extensive wet lab validation, which could provide more definitive evidence regarding the role of PSMC4 in lung adenocarcinoma." (PMID 40386560, 2025). "Modulating PSMC4 expression or its downstream pathways could offer new strategies for the treatment of lung adenocarcinoma, a prospect that warrants further investigation." (PMID 40386560, 2025). "We reveal an elevated level of PSMC4 in various malignancies, notably lung adenocarcinoma." (PMID 40386560, 2025).
lymph node metastasis (2 papers, 2022 to 2025). "Our statistical analyses confirm the relationship between PSMC4 overexpression and advanced pathological stages, suggesting its involvement in facilitating local invasion and lymph node metastasis." (PMID 40386560, 2025). "Across all six PSMC genes, only PSMC2 and PSMC4 exhibited a significant correlation with lymph node metastasis stage and neoplasm disease stage (p < .05), and groups with PSMC2 and PSMC4 overexpression had a higher number of patients with advanced lymph node metastasis and neoplasm disease stages." (PMID 36699466, 2022).
Obesity (2 papers, 2022 to 2023). Accumulation of substantial excess body fat. "Proteasome 26S subunit ATPase 4 (PSMC4) is a subunit of the 26S proteasome, which can regulate proteasome assembly, obesity." (PMID 37436074, 2023).
autism (1 paper, 2022). Persistent deficits in social interaction and communication and interaction as well as a markedly restricted repertoire of activity and interest as well as repetitive patterns of behavior. "DCAF12 and PSMC4 are both involved in the degradation of ubiquitinated proteins, but there have been no studies showing a relation between these two genes and autism." (PMID 36761165, 2022).
breast tumor (1 paper, 2010). "The first dataset includes relative expression levels of 6 reference genes (ACTB, GAPDH, MRPL19, PSMC4, PUM1, and SF3A1) quantified in 80 breast tumor samples." (PMID 20470420, 2010).
lung carcinoma (1 paper, 2025). "Considering the pivotal role of immune status in the survival of lung cancer patients, we also explored the impact of PSMC4 expression on immune cell infiltration." (PMID 40386560, 2025). "Furthermore, we conducted comprehensive in vitro and in vivo experiments to delineate the functional role of PSMC4 in the progression of lung cancer." (PMID 40386560, 2025). "Moreover, analysis of the GEO dataset GSE19804, which includes 60 lung cancer samples and 60 matched normal samples, consistently supported the upregulation of PSMC4 in lung cancer." (PMID 40386560, 2025). "We further delineated PSMC4’s functional roles through in vitro and in vivo studies on lung cancer cells, suggesting its utility in crafting targeted and personalized treatments that could enhance the prognosis of LUAD patients." (PMID 40386560, 2025). "These functional insights highlight the potential of PSMC4 as a therapeutic target, suggesting that inhibiting its expression or function could impede the progression of lung cancer." (PMID 40386560, 2025). "Moreover, colony formation assays aligned with these findings, further validating PSMC4’s pivotal role in modulating lung cancer cell proliferation." (PMID 40386560, 2025). "However, the role of PSMC4 in lung cancer remains largely unexplored." (PMID 40386560, 2025).
non-small cell lung carcinoma (1 paper, 2025). A group of at least three distinct histological types of lung cancer, including non-small cell squamous cell carcinoma, adenocarcinoma, and large cell carcinoma. "Immunohistochemical analysis of PSMC4 expression and its correlation with clinicopathological features in non-small cell lung cancer." (PMID 40386560, 2025).
tuberculous pleurisy (1 paper, 2021). "A total of eight possible biomarkers of tuberculous pleurisy were screened (RPL17, UBA7, NDUFB8, UQCRFS1, JUNB, PSMC4, PHPT1, and MAPK11)." (PMID 34925441, 2021).
tumor (15 papers, 2007 to 2025). "Within the immune environment of LUAD, the expression of PSMC4 is closely linked with the infiltration of specific immune cell subsets, underscoring its potential influence on tumor immune dynamics." (PMID 40386560, 2025). "Typically, Th2 cell activity is linked with a diminished anti-tumor response and heightened inflammatory conditions, consistent with the pro-tumorigenic influence of PSMC4." (PMID 40386560, 2025). "In vivo xenograft models have further validated these findings, showing that PSMC4 overexpression leads to increased tumor volume and weight." (PMID 40386560, 2025). "We extend these findings to LUAD, showing that high PSMC4 expression correlates significantly with increased T stage, N stage, and overall pathological stage, indicative of its role in promoting tumor aggressiveness and metastatic capacity." (PMID 40386560, 2025). "Results showed that PSMC4 knockdown significantly inhibited growth of tumour and reduced tumour weight." (PMID 37436074, 2023). "Cell counting kit‐8, cell apoptosis, cell cycle, wound healing, transwell and xenograft tumour model assays were performed to verify biological functions of PSMC4 in PCa." (PMID 37436074, 2023). "The overexpression of PSMC4 promoted the degradation of some key cell regulatory proteins, such as tumor suppressors, and further promoted the progression of tumors." (PMID 35223866, 2021). "Several factors may explain this: PSMC4 could enhance tumor growth by modulating tumor microenvironmental cells, such as immune and endothelial cells, promoting angiogenesis, and recruiting fibroblasts." (PMID 40386560, 2025). "PSMC4 gene present in module-1 showed high association with neoplasm (40%) as well as nervous system (30%) while it does not show association with immune system disease." (PMID 34918006, 2022). "The up-regulation of PSMC4 would contribute to this angiogenesis process for tumor metastasis." (PMID 23217164, 2012). "Moreover, our data highlight PSMC4’s involvement in crucial biological pathways that facilitate tumor progression and immune escape, such as the G2/M DNA damage checkpoint, Notch signaling, neutrophil extracellular trap formation, and the negative regulation of megakaryocyte differentiation." (PMID 40386560, 2025). "Thus, lower levels of PSMC4 could favor the accumulation of these beneficial immune cell types, potentially curtailing tumor growth." (PMID 40386560, 2025). "We procured tumor and adjacent normal tissue samples from 88 individuals diagnosed with NSCLC and scrutinized PSMC4 expression and its subcellular distribution using immunohistochemistry." (PMID 40386560, 2025). "Proteasome 26S subunit ATPase 4 (PSMC4), a proteasome subunit essential for protein degradation, influences tumor progression regulatory mechanisms." (PMID 40386560, 2025). "The effect of PSMC4 and PSMD6 expression in tumor progression is still unclear." (PMID 35497331, 2022). "In addition, PSMC4 knockdown markedly induced the cell apoptosis and inhibited cell proliferation, cell cycle and migration in DU145 cells, and PSMC4 knockdown significantly inhibited growth of tumour and reduced tumour weight in vivo." (PMID 37436074, 2023). "Additionally, the longer duration in xenograft models allows for metastasis and angiogenesis, and PSMC4 might aid immune evasion, further promoting tumor growth in the absence of functional immune surveillance." (PMID 40386560, 2025).
cancer (10 papers, 2012 to 2025). A tumor composed of atypical neoplastic, often pleomorphic cells that invade other tissues. "PSMC4 is a 26S protease that is involved in the ATP-dependent degradation of ubiquitinated proteins in the ubiquitin-proteasome system (UPS) that is extensively associated cancer pathogenesis." (PMID 23217164, 2012). "Through meticulous analysis of the TCGA and GTEx databases, we noted the ubiquitous overexpression of PSMC4 across various cancers, particularly LUAD." (PMID 40386560, 2025). "The cytoplasmic localization of PSMC4 in cancer cells indicates its involvement in proteasomal degradation pathways, which are commonly utilized by cancer cells to promote survival and proliferation." (PMID 40386560, 2025). "The correlation between high PSMC4 expression and advanced clinical T and N stages further emphasizes its role in driving cancer aggressiveness." (PMID 40386560, 2025). "Genes shared by cluster A and D represent a link between chromatin organization and cancer hallmark processes, involving FOXA1, ESRI, PHF14 and the ATPase proteasome subunits, PSMC5 and PSMC4." (PMID 38625038, 2024). "Furthermore, the KEGG pathway analysis elucidates the association of these genes with several cancer-related pathways, including transcriptional misregulation in cancer and viral carcinogenesis, pointing to a broader impact of PSMC4 on oncogenic processes." (PMID 40386560, 2025). "In addition, PSMC4 can also regulate the progression of multiple types of cancer, including breast cancer, endometrial cancer, PCa,11 oral squamous cell carcinoma." (PMID 37436074, 2023). "Proteasome 26S subunit ATPase 4 (PSMC4) could regulate cancer progression." (PMID 37436074, 2023). "Similarly, PSMC4, which is a member of the ATPase gene (PSMC) family and thus involved in protein degradation, has been reported to be related with cancer development and prognosis." (PMID 35634436, 2022). "Interestingly, we discovered that PSMC genes were overexpressed in a subtype-specific manner: specifically, PSMC1, PSMC2, PSMC3, PSMC4 were highly expressed in the triple-negative subtype, PSMC5 in HER-2, and PSMC6 in luminal cancer." (PMID 34329194, 2021). "Several genes (B2M, EIF2B1, ELF1 and PSMC4; type 1 EC, and YWAZ, UBC, and PGK1; type 2 EC) were not identified in the combinations of five best genes for the two cancer sub-types (this study) suggesting that the transcriptome of these two EC sub-types may in fact be very different." (PMID 32439920, 2020).
PSMC4 also shares sentences with these, for which no sentence is quoted: cervical cancer (2 papers); neurodegenerative disease (2); ovarian carcinoma (2); Alzheimer disease (1); Atrophy (1); bladder cancer (1); Bladder Urothelial Carcinoma (1); Brain atrophy (1); carcinosarcoma (1); cholangiocarcinoma (1); Epstein-Barr virus infection (1); gastric cancer (1); Glioblastoma multiforme (1); glottic carcinomas (1); head and neck cancer (1); hepatocellular carcinoma (1); hypopharyngeal carcinoma (1); immune system disease (1); infection (1); kidney renal cancer (1); Kyphosis (1); liver cancer (1); melanoma (1); muscular dystrophies (1); myopathies (1); oesophageal cancer (1); Oral Squamous Cell Carcinoma (1); pancreatic cancer (1); Parkinson's (1); spinocerebellar ataxia (1).
A further 2 diseases each share a sentence with PSMC4 in 1 paper.